RNU6-969P (RNA, U6 small nuclear 969, pseudogene)
Gene: Small nuclear RNA gene on chromosome 1 (52,805,108 to 52,805,212, reverse strand). Ensembl gene ENSG00000206627.
Homologues: Orthologues: chimpanzee U6 (99% identical), macaque U6 (92% identical), dog U6 (82% identical), mouse Gm23691 (82% identical), pig U6 (81% identical), guinea pig U6 (77% identical), rabbit U6 (75% identical). Paralogues in human: RNU6-1152P (88% identical), RNU6-49P (88% identical), RNU6-820P (88% identical), RNU6-12P (87% identical), RNU6-13P (87% identical), RNU6-25P (87% identical), RNU6-31P (87% identical), RNU6-32P (87% identical), RNU6-41P (87% identical), RNU6-761P (87% identical), RNU6-1 (86% identical), RNU6-1122P (86% identical), and 1286 more.